IL18BP (interleukin 18 binding protein)
Description:
Isoform A binds to IL-18 and inhibits its activity. Functions as an inhibitor of the early TH1 cytokine response.
Synonyms: IL18BPa; FVH
Tractability: Antibody: UniProt places it where antibodies can reach, with high confidence; its Gene Ontology location is reachable by antibodies, with high confidence; UniProt predicts a signal peptide or a membrane-spanning region.
Gene: Protein-coding gene on chromosome 11 (71,998,613 to 72,007,315, forward strand). Ensembl gene ENSG00000137496.
Subcellular location: Secreted
Subcellular location (Human Protein Atlas): Endoplasmic reticulum; Predicted to be secreted
Pathways (Reactome):
Immune System: Interleukin-18 signaling; Interleukin-37 signaling
Gene Ontology:
Molecular function: interleukin-18 binding; protein binding; receptor antagonist activity
Biological process: T-helper 1 type immune response; negative regulation of T-helper 1 type immune response; cellular response to hydrogen peroxide; cellular response to tumor necrosis factor; response to lipopolysaccharide
Cellular component: decoy receptor complex; extracellular exosome; extracellular region
Genetic constraint (gnomAD): Loss-of-function variants: 25 observed, 22.3 expected, observed/expected ratio (o/e) 1.12, 90% interval 0.82 to 1.56. The upper end of that interval is the gene's LOEUF score, 1.56, which puts it in group 6 of 6, group 1 being the genes least tolerant of losing a copy. Missense variants: 239 observed, 251.96 expected, observed/expected ratio (o/e) 0.95, 90% interval 0.85 to 1.06. Synonymous variants: 107 observed, 106.59 expected, observed/expected ratio (o/e) 1, 90% interval 0.86 to 1.18.
Homologues: Orthologues: chimpanzee IL18BP (99% identical), macaque IL18BP (88% identical), guinea pig IL18BP (66% identical), mouse Il18bp (62% identical), rat Il18bp (62% identical), rabbit IL18BP (61% identical).
Diseases named in the same sentence as IL18BP in open-access papers:
IL18BP is named in the same sentence as 122 diseases in open-access papers, as found by Europe PMC text mining. Sharing a sentence is not in itself a finding about the gene and the disease. The quoted sentences say what the papers report.
systemic lupus erythematosus (10 papers, 2010 to 2025). An autoimmune multi-organ disease typically associated with vasculopathy and autoantibody production. "Dysregulation of the IL-18/IL-18BP axis results in excessive bioactivity of free IL-18, a key mediator of inflammation in systemic lupus erythematosus (SLE) and lupus nephritis (LN)." (PMID 41142814, 2025). "Imbalance of IL-18/IL-18BP in patients was reported in several diseases, such as hemophagocytic syndrome and systemic lupus erythematosus, but IL-18BP was only moderately elevated even under the active stage." (PMID 33922655, 2021). "IL-18BP also acts to reduce IL-18 agonist activity and an imbalance of IL-18 and IL-18BP has been described in Wegener’s granulomatosis and systemic lupus erythematosus." (PMID 33643264, 2021). "In Wegener’s granulomatosis and systemic lupus erythematosus, the serum levels of IL-18BP and IL-18 were high, but the level of IL-18BP was insufficient to neutralize IL-18 and the level of free IL-18 was higher than that of healthy individuals." (PMID 30717382, 2019). "This fact should be taken into account when the results of two other studies are contemplated, in which a dysregulation of the IL-18/IL-18BP equilibrium in systemic lupus erythematosus (SLE) and Wegener's granulomatosis (WG) was reported." (PMID 20072626, 2010). "Some previous reports demonstrated the importance of the balance between IL-18 and IL-18BP in inflammatory bowel disease, in rheumatoid arthritis, and in systemic lupus erythematosus which may help to understand our finding that plasma level IL-18 correlated well with IL-18BP level in eczema." (PMID 28839348, 2017). "To functionally test this, we blocked IFNγ production using IL-18BP and type I IFN signaling using the anti-IFN α receptor 1 (IFNAR1) antibody anifrolumab, which is in clinical trials to treat systemic lupus erythematosus." (PMID 35930640, 2022).
colitis (9 papers, 2017 to 2025). Inflammation of the colon. "Excessive IL-18 production, as observed in conditions involving the deletion of IL-18BP or colitis, has been linked to the loss of mucus-producing goblet cells." (PMID 41116055, 2025). "In a colitis model, IL-18 acted directly on intestinal epithelial cells to enhance inflammation, thereby exacerbating colitis via excessive IL-18 stimulation in IL-18BP-deficient mice." (PMID 30717382, 2019). "IL-18/IL-18R signaling in intestinal epithelial cells was also shown to drive DSS colitis in mice, whereas IL-18BP protected mice from colitis, suggesting a colitogenic function of IL-18." (PMID 33562334, 2021). "For example, the administration of IL-18BP was found to substantially reduce pathology in murine models of experimental arthritis, colitis, endotoxic shock, and type 1 diabetes." (PMID 28900426, 2017). "Providing further support for this, we found that administering recombinant IL-18BP to CarinhKO mice reversed the severe colitis phenotype of CarinhKO mice, as evidenced by our histological observations and the ultimate restoration of body weight and colon length." (PMID 37055591, 2023). "Moreover, analysis of colon homogenates from a DSS-induced colitis model mice showed that the protein levels of IL-18BP were significantly reduced in CarinhKO mice, compared with their WT littermates." (PMID 37055591, 2023). "When colitis is triggered, Carinh/IRF1 regulates the induction of the anti-inflammatory factor IL-18BP to prevent further inflammation and colitis exacerbation." (PMID 37055591, 2023). "In this respect, considering the effective treatment of a critically ill neonatal AIFEC patient with recombinant IL-18BP, it is quite remarkable that additional IL-18BP deletion did not allow IL-18 to provoke spontaneous colitis in NLRC4V341A/V341A mice." (PMID 38090573, 2023). "One recent report demonstrated exacerbated colitis and arrested maturation of goblet cells in the absence of IL-18BP." (PMID 28900426, 2017). "A 16-gene signature (CARD12, CCL3, CCR3, CXCL1, F5, FAM210B, GADD45A, IL18bp, IL2RA, IL5, IL8, MMP9, PTGS2, SOCS3, TLR9 and UBE2C) was identified from 30 days post-tremelimumab initiation blood that discriminated patients developing grade 0–1 from grade 2–4 diarrhea/colitis." (PMID 30227886, 2018).
rheumatoid arthritis (9 papers, 2012 to 2025). A chronic, systemic autoimmune disorder characterized by inflammation in the synovial membranes and articular surfaces. "IL-18BP is a natural antagonist of pro-inflammatory IL-18 cytokine linked to autoimmune disorders like rheumatoid arthritis." (PMID 27649785, 2016). "Alternatively, IL-18 binding protein (IL-18BP), used as a decoy receptor for IL-18, attenuated levels of IL-17A production in a rheumatoid arthritis model." (PMID 40777291, 2025). "Administration of IL-18BP reduced inflammation in a model of rheumatoid arthritis; however, at high concentrations IL-18BP also bound IL-37 and the anti-inflammatory effect was lost." (PMID 33643264, 2021). "Patients with rheumatoid arthritis (RA) have increased levels of interleukin-18 (IL-18) and decreased levels of IL-18 binding protein (IL-18BP) in the serum and synovial fluid (SF) compared to those in patients with osteoarthritis (OA) or in healthy controls." (PMID 34530864, 2021). "At low dosing of IL-18BP, there is reduced inflammation in a model of rheumatoid arthritis but as the doing of IL-18BP increases, the anti-inflammatory properties of IL-18BP are lost." (PMID 24115947, 2013). "A phase I study, has shown that in healthy volunteers, rheumatoid arthritis and psoriasis patients subcutaneous injections of IL-18BP are well tolerated and within 1–2 weeks show steady levels of the protein in serum." (PMID 22761702, 2012). "Recombinant human IL-18BP has been shown to be as potent as the natural IL-18BP and to be safe in preliminary human trials conducted in psoriasis or rheumatoid arthritis." (PMID 22891066, 2012). "The biological association between ACAN and IL-18BP is not clear, but IL-18BP have shown to suppress IL-17-induced osteoclastogenesis and rectifies T cell imbalance in rheumatoid arthritis." (PMID 40625747, 2025). "Although unlike in rheumatoid arthritis, that the expression of IL-18BP was decreased, it is observed that both plasma levels of IL-18 and IL-18BP in eczema were increased." (PMID 28839348, 2017).
autoimmune disease (7 papers, 2016 to 2025). A disorder resulting from loss of function or tissue destruction of an organ or multiple organs, arising from humoral or cellular immune responses of the individual to their own tissue constituents. "IL-18 and IL-18BP are associated with various diseases, including autoimmune disorders, inflammatory conditions, infectious diseases, and cancer (Mühl & Bachmann, 2019)." (PMID 39769266, 2024). "The action of IL-18 is tightly regulated by IL-18 binding protein (IL-18BP) and in autoimmune diseases, the serum IL-18/IL-18BP ratio is associated with disease severity." (PMID 31978079, 2020). "Dinarello revisited the role of IL-18 in autoimmune diseases and the activity of its natural regulator, IL-18 binding protein (IL-18BP)." (PMID 41417343, 2025). "The importance of the IL-18/IL-18BP dyad lies in its ability to balance the immune system, making it a potential therapeutic target for autoimmune disorders, inflammatory diseases and cancer, conditions that require precise immune modulation." (PMID 39769266, 2024). "We assume an upregulation of IL18BP in IBDV-infected BF of chickens as a self-negative regulation mechanism to reduce inflammation inside the bursal tissue as targeting IL-18 with IL18BP is an achievable treatment for autoimmune disease in humans." (PMID 34147086, 2021). "Accumulating evidences indicate the therapeutic effects of neutralizing anti-IL-18 antibody and IL-18 binding protein (IL-18BP) in various autoimmune diseases, inflammatory bowel disease, sepsis, and acute kidney injury." (PMID 27888626, 2016). "For example, in autoimmune diseases characterized by excessive IL-18 activity, blocking IL-18 or enhancing IL-18BP function could be beneficial." (PMID 39769266, 2024). "In this review, we address the difference in the biological activity of IL-18BP isoforms, in the immunity balancing Th1 and Th2 immune response, its critical role in autoimmune diseases, as well as current clinical trials of recombinant IL-18BP (rIL-18BP) or equivalent." (PMID 35885055, 2022). "Indeed, blocking the action of IL-18 using recombinant human IL-18BP (Tadekinig Alfa) is in late stage clinical trials for a number of autoimmune disorders." (PMID 31978079, 2020). "Tadekinig alfaTM, a recombinant IL-18BP, is in phase III clinical study for inflammatory and autoimmune diseases." (PMID 36875111, 2023).
macrophage activation syndrome (7 papers, 2023 to 2026). A complication of rheumatic disease that is caused by excessive activation and uncontrolled proliferation of T lymphocytes and well-differentiated macrophages. "The dysregulation of IL‐18 and IL‐18BP is significantly associated with immune‐mediated diseases, especially those where IFNγ plays a pathological role, such as macrophage activation syndrome (MAS)." (PMID 41532007, 2026). "A child with IBD and macrophage activation syndrome (MAS) caused by an NLR family CARD domain-containing protein 4 (NLRC4) gain-of-function (GOF) gene variant was reported to respond to recombinant human IL-18BP." (PMID 39458007, 2024). "It is known that inactivating inflammatory responses is critical, and that IL-18BP is involved to some extent as reduced inactivation of IL-18 by IL-18BP is a key component of macrophage activation syndrome." (PMID 41592067, 2026). "In this scenario, IL-18BP expression is elevated by interferon-γ as part of the inflammatory response and limits the effects of IL-18 reducing the likelihood of macrophage activation syndrome a potentially fatal over-stimulation of the immune response." (PMID 41592067, 2026). "However, emerging evidence indicates that the IL-18/IL-18BP balance could be dysregulated in macrophage activation syndrome (MAS), as mirrored by the presence of free IL-18 in the circulation of patients with MAS." (PMID 37074208, 2023).
adult-onset Still disease (6 papers, 2019 to 2022). A rare inflammatory multisystem disorder characterized clinically by fever of unknown origin, arthralgia or arthritis, hyperleucocytosis, and typical skin rash. "A recent Phase II trial of recombinant IL-18BP (tadekinig alfa) showed promising results for adult-onset Still's disease." (PMID 34917629, 2021). "Recently, a phase II study of IL-18BP in adult-onset Still’s disease has been conducted, and it showed clinical efficacy via decreasing inflammatory marker and skin lesions." (PMID 34530864, 2021). "The dosage, method of administration, and interval of the previous phase II study of adult-onset Still’s disease may be referred to in further clinical trials of IL-18BP on patients with RA." (PMID 34530864, 2021). "Moreover, systemic juvenile idiopathic arthritis or adult-onset Still’s disease are also characterized by high serum IL-18 concentrations and are treated by IL-18BP (binding protein).." (PMID 32297262, 2020). "Clinical trials are underway to investigate the treatment of adult-onset Still’s disease and NLRC4-related macrophage activation syndrome (inflammatory diseases associated with high plasma IL-18 levels) using IL-18BP (ClinicalTrials.gov Identifier: NCT 02398435, NCT 03113760)." (PMID 30717382, 2019). "Adult-onset Still’s disease is a multi-systemic inflammatory disease characterized by upregulated IL-18 levels and downregulated IL-18BP in the circulation, mediated by an unknown mechanism." (PMID 30717382, 2019). "Therefore, elevated miR-134 in adult-onset Still’s disease might induce the upregulation of IL-18 by inhibiting IL18BP, and therefore, miR-134 might be a potential biomarker for this disease." (PMID 30717382, 2019).
asthma (6 papers, 2018 to 2024). "It has also been shown that the expression of IL-18BP in the blood of asthma patients is 13 times higher than that of IL-18, suggesting excessive inhibition of IL-18 by IL-18BP in asthma." (PMID 38727246, 2024). "The expression of IL‐18, IL‐18BP and IL‐18Rα was examined in subjects with asthma and healthy controls in bronchial biopsies by immunohistochemistry and IL‐18 and IL‐18BP release in sputum." (PMID 34194747, 2021). "We demonstrated that 13‐fold more monocytes, 17.5‐fold more neutrophils and 4.1‐fold more B cells express IL‐18BP than IL‐18 in asthmatic blood, suggesting that there is excessive amount of IL‐18BP to abolish actions of IL‐18 in asthma." (PMID 28922563, 2018). "Because monocytes/macrophages, neutrophils and B cells are involved in the pathogenesis of asthma, and they have close relationship with IL‐18, we first examined expression of IL‐18, IL‐18BP and IL‐18R in these cells." (PMID 28922563, 2018). "We therefore believe that actions of IL‐18 in asthma depend on the balance between IL‐18 and IL‐18BP." (PMID 28922563, 2018). "Little is known about expression of IL‐18, IL‐18BP and IL‐18R in peripheral blood B cells, and we therefore examined expression of them in B cells of asthma patients." (PMID 28922563, 2018). "We therefore examined expression of IL‐18, IL‐18BP and IL‐18R in parallel in inflammatory cells of asthma." (PMID 28922563, 2018). "To further understand the involvement of IL‐18 in asthma, we examined expression of IL‐18, IL‐18BP and IL‐18R in peripheral blood neutrophils." (PMID 28922563, 2018). "A 13‐fold (95%/7.3%) more monocytes, 17.5‐fold (70%/4%) more neutrophils and 4.1‐fold (69.3%/17%) more B cells express IL‐18BP than IL‐18 indicate that there is excessive amount of IL‐18BP to completely abolish actions of IL‐18 in asthma." (PMID 28922563, 2018). "Our data clearly indicate that the role of IL‐18 in asthma is very likely to be determined by balance of IL‐18/IL‐18BP/IL‐18R expression in inflammatory cells." (PMID 28922563, 2018). "Using ELISA kits, we observed that levels of IL‐18 were 270.7 and 169.0 pg/ml, and levels of IL‐18BP were 3460 and 1910 pg/ml in the plasma of patients with asthma and HC volunteers, respectively." (PMID 28922563, 2018). "In asthma, the interplay between IL‐18, IL‐18BP and IL‐18R20, 21 is poorly understood and whether the IL‐18 axis impacts epithelial repair or EMT‐associated cell protein or gene expression is unknown." (PMID 34194747, 2021). "To test our hypothesis, we investigated IL‐18, IL‐18BP and IL‐18Rα expression in bronchial biopsies and quantified sputum cytokine release in asthma and healthy controls." (PMID 34194747, 2021). "An imbalance between IL‐18 and IL‐18BP expression may account for increased IL‐18 activity in asthma." (PMID 28922563, 2018). "However, DAE seemed to induce elevated MFI of IL‐18 and IL‐18BP (Fig. 4Gii and I) in B cells of asthma patients." (PMID 28922563, 2018). "As for IL‐18BP, there should be 1.28% (64% × 2%) monocyte‐derived, 1.19% (1.7% × 70%) neutrophil‐derived and 0.045% (2.8% × 1.6%) B‐cell‐derived IL‐18R+ leucocytes in asthma blood." (PMID 28922563, 2018). "However, little is known about influence of allergens on expression of IL‐18, IL‐18BP and IL‐18R in asthma." (PMID 28922563, 2018). "The ratio between plasma concentrations of IL‐18 and IL‐18BP was 1:12.8 in asthma patients." (PMID 28922563, 2018). "However, little is known about expression of IL‐18BP and IL‐18R in monocytes, neutrophils and B cells in asthma." (PMID 28922563, 2018). "A report that a severe IL‐18/IL‐18BP imbalance results in Th1 lymphocyte and macrophage activation in patients with secondary haemophagocytic syndrome 25 may support the view that an IL‐18/IL‐18BP imbalance decides the role of IL‐18 in the pathogenesis of asthma." (PMID 28922563, 2018). "Therefore, IL‐18R blocking or IL‐18BP activity enhancing therapies may be useful for treatment of asthma." (PMID 28922563, 2018).
asthma (continued). "The observations that sensitization increased number of IL‐18BP+ macrophages, and that IL‐18 up‐regulated expression of IL‐18BP in lung macrophages of sensitized mice indicate that certain allergen may eliminate contribution of IL‐18 to asthma via IL‐18BP+ macrophages." (PMID 28922563, 2018). "In contrast, the IL‐18BP was decreased in the lamina propria in asthma and was absent in the bronchial epithelium." (PMID 34194747, 2021). "The IL‐18BP lamina propria was decreased in subjects with asthma compared with healthy controls (P = 0.007) and between mild moderate and severe asthma groups (P = 0.047) but not in ASM cells." (PMID 34194747, 2021). "Serum IL‐18 level was found significantly higher in children who had asthma 5, but the plasma/serum level of IL‐18BP in asthma, and correlation between IL‐18 and IL‐18BP has not been investigated." (PMID 28922563, 2018). "As macrophages are the major source of IL‐18BP within the submucosa 29, it is not difficult to understand IL‐18 is unlikely to contribute to the pathogenesis of asthma through lung macrophages." (PMID 28922563, 2018).